KRT72 (keratin 72)
Description:
Has a role in hair formation. Specific component of keratin intermediate filaments in the inner root sheath (IRS) of the hair follicle (Probable).
Synonyms: CK-72; K72; K6IRS2; KRT6; KRT6IRS2; K6irs
Tractability: PROTAC: ubiquitination databases record sites on it.
Gene: Protein-coding gene on chromosome 12 (52,585,589 to 52,601,538, reverse strand). Ensembl gene ENSG00000170486.
Pathways (Reactome):
Developmental Biology: Formation of the cornified envelope; Keratinization
Gene Ontology:
Molecular function: protein binding; structural constituent of skin epidermis
Biological process: intermediate filament organization; keratinization
Cellular component: extracellular exosome; cytosol; keratin filament
Genetic constraint (gnomAD): Loss-of-function variants: 40 observed, 43.87 expected, observed/expected ratio (o/e) 0.91, 90% interval 0.71 to 1.19. The upper end of that interval is the gene's LOEUF score, 1.19, which puts it in group 5 of 6, group 1 being the genes least tolerant of losing a copy. Missense variants: 733 observed, 657.62 expected, observed/expected ratio (o/e) 1.11, 90% interval 1.05 to 1.18. Synonymous variants: 301 observed, 281.71 expected, observed/expected ratio (o/e) 1.07, 90% interval 0.97 to 1.17.
Homologues: Orthologues: chimpanzee KRT72 (97% identical), dog KRT72 (86% identical), rabbit KRT72 (84% identical), mouse Krt72 (83% identical), pig KRT72 (83% identical), rat Krt72 (82% identical), guinea pig KRT72 (77% identical). Paralogues in human: KRT73 (75% identical), KRT71 (74% identical), KRT74 (73% identical), KRT3 (61% identical), KRT6A (60% identical), KRT76 (60% identical), KRT6B (60% identical), KRT6C (60% identical), KRT4 (59% identical), KRT5 (59% identical), KRT2 (58% identical), KRT75 (57% identical), and 56 more.
Diseases named in the same sentence as KRT72 in open-access papers:
KRT72 is named in the same sentence as 41 diseases in open-access papers, as found by Europe PMC text mining. Sharing a sentence is not in itself a finding about the gene and the disease. The quoted sentences say what the papers report.
glioma (1 paper, 2021). A benign or malignant brain and spinal cord tumor that arises from glial cells (astrocytes, oligodendrocytes, ependymal cells). "It has been demonstrated that transcriptionally active genes in gliomas such as calmodulin (CALM1) are characterized by active histone marks, whereas transcriptionally silent genes, such as keratin 72 (KRT72), display repressive histone modifications." (PMID 33430434, 2021).
hypotrichosis 8 (1 paper, 2023). Any hypotrichosis in which the cause of the disease is a mutation in the LPAR6 gene. "In addition, some paralog genes Krt25, Krt27, Krt72, Krt75, and Krt85, which also participate in the formation of keratin intermediate filaments in the IRS, could be related to Woolly Hair, Autosomal Recessive 3, and Hypotrichosis 8, which were significantly decreased in Krt71–KO mice." (PMID 37443815, 2023).
KRT72 also shares sentences with these, for which no sentence is quoted: psoriasis (18 papers); tumor (17); cancer (9); bladder cancer (4); breast carcinoma (3); hepatocellular carcinoma (3); dermatitis (2); diabetic foot ulcer (2); head and neck squamous cell carcinoma (2); lung carcinoma (2); oral squamous cell carcinoma (2); psoriasis vulgaris (2); serous ovarian carcinomas (2); skin cancer (2); squamous cell carcinoma (2); actinic keratosis (1); bladder tumors (1); cervical cancer (1); colorectal cancer (1); cystitis (1); dental caries (1); discoid lupus erythematosus (1); ductal carcinomas (1); Erythema (1); gastric carcinoma (1); head and neck cancer (1); lichen planus (1); melanoma (1); nasopharyngeal carcinoma (1); oral cancer (1).
A further 9 diseases each share a sentence with KRT72 in 1 paper.